SLC44A2 (solute carrier family 44 member 2 (CTL2 blood group))
Description:
[Isoform 1]: Choline/H+ antiporter, mainly in mitochondria. Also acts as a low-affinity ethanolamine/H+ antiporter, regulating the supply of extracellular ethanolamine (Etn) for the CDP-Etn pathway, redistribute intracellular Etn and balance the CDP-Cho and CDP-Etn arms of the Kennedy pathway. [Isoform 3]: Does not exhibit choline transporter activity.
Synonyms: CTL2; HNA-3; PP1292
Tractability: Antibody: UniProt places it where antibodies can reach, with high confidence; its Gene Ontology location is reachable by antibodies, with high confidence; UniProt predicts a signal peptide or a membrane-spanning region. PROTAC: ubiquitination databases record sites on it; its protein half-life has been measured.
Gene: Protein-coding gene on chromosome 19 (10,602,457 to 10,644,558, forward strand). Ensembl gene ENSG00000129353.
Subcellular location: Cell membrane; Mitochondrion outer membrane
Subcellular location (Human Protein Atlas): Cell Junctions; Vesicles
Pathways (Reactome):
Metabolism: Choline catabolism; Synthesis of PC
Immune System: Neutrophil degranulation
Transport of small molecules: SLC-mediated bile acid transport
Gene Ontology:
Molecular function: choline transmembrane transporter activity; ethanolamine transmembrane transporter activity; transmembrane transporter activity
Biological process: choline transport; ethanolamine transport; positive regulation of canonical NF-kappaB signal transduction; transmembrane transport; bile acid and bile salt transport; choline catabolic process; phosphatidylcholine biosynthetic process
Cellular component: extracellular exosome; lysosomal membrane; mitochondrial outer membrane; mitochondrion; plasma membrane; membrane; specific granule membrane
Genetic constraint (gnomAD): Loss-of-function variants: 60 observed, 94.74 expected, observed/expected ratio (o/e) 0.63, 90% interval 0.51 to 0.79. The upper end of that interval is the gene's LOEUF score, 0.79, which puts it in group 3 of 6, group 1 being the genes least tolerant of losing a copy. Missense variants: 791 observed, 952.66 expected, observed/expected ratio (o/e) 0.83, 90% interval 0.78 to 0.88. Synonymous variants: 355 observed, 371.31 expected, observed/expected ratio (o/e) 0.96, 90% interval 0.88 to 1.04.
Homologues: Orthologues: macaque SLC44A2 (97% identical), chimpanzee SLC44A2 (97% identical), rabbit SLC44A2 (93% identical), rat Slc44a2 (92% identical), mouse Slc44a2 (91% identical), pig SLC44A2 (90% identical), guinea pig SLC44A2 (89% identical), zebrafish slc44a2 (68% identical), tropical clawed frog slc44a2 (66% identical), dog SLC44A2 (62% identical), zebrafish SLC44A2 (58% identical). Paralogues in human: SLC44A5 (54% identical), SLC44A4 (53% identical), SLC44A1 (27% identical), SLC44A3 (26% identical).
Diseases named in the same sentence as SLC44A2 in open-access papers:
SLC44A2 is named in the same sentence as 58 diseases in open-access papers, as found by Europe PMC text mining. Sharing a sentence is not in itself a finding about the gene and the disease. The quoted sentences say what the papers report.
Venous thrombosis (7 papers, 2019 to 2025). Formation of a blood clot (thrombus) inside a vein, causing the obstruction of blood flow. "Consistent with this, mice deficient in SLC44A2 are protected against experimental venous thrombosis." (PMID 39908367, 2025). "Genome-wide association studies have linked the expression of the human neutrophil antigen 3b epitope on the SLC44A2 protein with a 30% decreased risk of venous thrombosis." (PMID 38916960, 2024). "Recent studies have linked SLC44A2 single-nucleotide polymorphism (SNP) loci with venous thrombosis and Ménière disease." (PMID 38916960, 2024). "Taken together, these data reveal a previously unreported mode of platelet-neutrophil crosstalk, mechanosensitive NET production, and provide mechanistic insight into the protective effect of the SLC44A2 rs2288904-A polymorphism in venous thrombosis." (PMID 32314961, 2020). "Recent data reveal that SLC44A2-deficient mice exhibit normal hemostatic responses but are protected against development of venous thrombosis, provide further encouragement for this strategy." (PMID 32314961, 2020). "Two polymorphisms in SLC44A2 (rs2288904, rs9797861) were linked to venous thrombosis, coronary artery disease, and stroke, and rs2288904 was associated with severity of MD." (PMID 32038468, 2019). "Significantly upregulated RSAD2 is involved in the process of spinal cord injury and is associated with the staging, grading, and lymphatic metastasis of malignant tumors, while SLC44A2 is associated with ventricular tachycardia and the formation of venous thrombosis." (PMID 38891594, 2024). "Likewise, the SLC44A2 rs2288904-A polymorphism showed protective effect in venous thrombosis, implicating its potential role in stroke by modulating thrombosis." (PMID 35449099, 2022). "A polymorphism in SLC44A2 (rs2288904-A) present in 22% of the population causes an R154Q substitution in an extracellular loop of SLC44A2 that is protective against venous thrombosis results in severely impaired binding to both activated αIIbβ3 and VWF-primed platelets." (PMID 32314961, 2020). "Moreover, mice deficient in SLC44A2 are protected against venous thrombosis in the stenosis model." (PMID 39908367, 2025). "CTL2 gene SLC44A2 is well-established the human neutrophil antigen, and genetic risk factor for hearing loss, Meniere’s disease, and venous thrombosis." (PMID 33789160, 2021). "SLC44A2 knockout mouse is protected against venous thrombosis showing that CTL2 could be an important therapeutic target for the disease." (PMID 33789160, 2021).
hearing loss (6 papers, 2015 to 2023). "In accordance with Slc44a2−/− and Slc44a2+/− mice, the SLC44A2 null allele in proband 2 and her siblings is associated with progressive age‐related hearing impairment." (PMID 36695047, 2023). "The VER+ siblings with a heterozygous deletion of SLC44A2 only suffer from hearing loss, while the wild‐type VER+ sibling is healthy." (PMID 36695047, 2023). "SLC44A2 (solute carrier 44a2), also known as CTL2 (choline transporter-like protein 2), is expressed in many supporting cell types in the cochlea and is implicated in hair cell survival and antibody-induced hearing loss." (PMID 26463873, 2015). "Interestingly, the first‐ever reported SLC44A2‐deficient individuals suffer from progressive hearing impairment, recurrent arterial aneurysms, and epilepsy." (PMID 36695047, 2023). "Furthermore, KHRI-3 binding to SLC44A2 interferes with a supporting cell function that is essential for hair cell survival, since hair cells begin to die and hearing loss ensues after antibody binding." (PMID 26463873, 2015). "Furthermore, in vivo binding of anti-SLC44A2 antibody induced hearing loss in mice and guinea pigs." (PMID 32038468, 2019).
Stroke (4 papers, 2019 to 2023). Sudden impairment of blood flow to a part of the brain due to occlusion or rupture of an artery to the brain. "Although the rest of 16 causal genes identified by the integrative analysis were only replicated in one or two analyses, some of them (e.g. ALDH2, CDK6, HDAC9, and SLC44A2) were previously reported linked to stroke, which also demonstrate the reliability of our integrative analysis in a way." (PMID 35449099, 2022). "The SNP in SLC44A2 identified by GWAS studies that is protective against VTE and stroke (rs2288904-A) causes a missense mutation (R154Q) in the first 178a.a." (PMID 32314961, 2020). "From this list, SLC44A2 stood out due to its recent identification as a risk locus for both VTE and stroke, but with as yet unknown functional association with these pathologies." (PMID 32314961, 2020). "From the remaining 30 candidate genes, the SLC44A2 gene was selected for validation due to its recent identification as a risk locus for both DVT and stroke, both of which are pathologies associated with described contributions of platelet-leukocyte interactions." (PMID 32314961, 2020).
acute lung injury (2 papers, 2023 to 2024). A condition of lung damage that is characterized by bilateral pulmonary infiltrates (pulmonary edema) rich in neutrophils, and in the absence of clinical heart failure. "SLC44A2 deficiency has been associated with hair cell loss, spiral ganglion degeneration, and hearing loss in mice, and with Ménière disease and transfusion-related acute lung injury in humans." (PMID 38916960, 2024).
aortic aneurysm (2 papers, 2024). A ruptured aneurysm located in the wall of the proximal portion of the descending aorta proceeding from the arch of the aorta. "Elevated SLC44A2 in aortic aneurysm is associated with upregulated runt-related transcription factor 1 (RUNX1)." (PMID 38916960, 2024). "VSMC-specific SLC44A2-knockout mice were more susceptible to aortic aneurysm under Ang II infusion, while SLC44A2 overexpression showed protective effects." (PMID 38916960, 2024). "VSMC-specific SLC44A2 deficiency aggravates the development of Ang II–induced aortic aneurysm." (PMID 38916960, 2024). "The results showed that the protective effect of LEN was totally abolished by SLC44A2 deficiency, as evidenced by unimproved aortic aneurysm incidence, aortic diameter expansion, aortic rupture rate, elastin breakage, and MMP activation in Ang II–infused Slc44a2SMKO mice treated with LEN." (PMID 38916960, 2024). "Increased SLC44A2 in VSMCs is associated with aortic aneurysm." (PMID 38916960, 2024). "Although SLC44A2 was upregulated in aortic aneurysm tissues from humans and mice, we found a profound suppressive effect of SLC44A2 on aortic aneurysm development." (PMID 38916960, 2024). "LEN inhibits VSMC phenotypic switching by modulating the RUNX1/SLC44A2 axis and improves the aortic pathology in mouse aortic aneurysm models, revealing a potential prospect for clinical application in humans." (PMID 38916960, 2024). "This suggested the compensatory effect of SLC44A2 on maintaining the contractile phenotype of VSMCs during the development of aortic aneurysm." (PMID 38916960, 2024). "Taken together, these findings demonstrate that SLC44A2 suppresses Ang II–induced medial degeneration and restores the integrity of the arterial wall, thus protecting against aortic aneurysm." (PMID 38916960, 2024). "Taken together, these results show that upregulation of RUNX1 in VSMCs accounts for the induction of SLC44A2 during aortic aneurysm." (PMID 38916960, 2024). "Taken together, these data demonstrate that LEN activates TGF-β/SMAD signaling via SLC44A2 to prevent aortic aneurysm." (PMID 38916960, 2024). "Venn diagram analysis based on microarray and single-cell RNA sequencing identified SLC44A2 as a major regulator of VSMC phenotypic switching in aortic aneurysm." (PMID 38916960, 2024). "We found that the upregulated RUNX1 in VSMCs contributed to the compensating increase in SLC44A2 during aortic aneurysm." (PMID 38916960, 2024). "Taken together, these results directed our focus toward the functional role of SLC44A2 in aortic aneurysm." (PMID 38916960, 2024). "Furthermore, low-dose lenalidomide (LEN; 20 mg/kg/day) suppressed aortic aneurysm progression by enhancing SLC44A2 expression." (PMID 38916960, 2024). "Strikingly, SLC44A2 overexpression in VSMCs blunted aortic aneurysm incidence induced by Ang II." (PMID 38916960, 2024). "First, SLC44A2 was adaptively augmented in aortic aneurysm lesions from humans and mice." (PMID 38916960, 2024). "VSMC-specific SLC44A2 overexpression ameliorates Ang II–induced aortic aneurysm." (PMID 38916960, 2024). "Overexpression of SLC44A2 in VSMCs mitigated the vascular remodeling of aortic aneurysm, while VSMC-specific knockout of SLC44A2 aggravated the development of aortic aneurysm in Ang II–infused mice." (PMID 38916960, 2024). "To unravel the molecular basis of SLC44A2 upregulation in aortic aneurysm, we integrated the prediction of SLC44A2 promoter–binding transcription factors with digital gene expression (DGE) analysis of aortic RNAs from human and murine aortic aneurysm samples." (PMID 38916960, 2024). "This study elucidates the critical role of SLC44A2 in regulating VSMC phenotypic switching and its implication in aortic aneurysm development." (PMID 38916960, 2024). "We demonstrated here that enhanced SLC44A2 expression acts as an adaptive program in VSMCs that attenuates VSMC dedifferentiation and protects against aortic aneurysm." (PMID 38916960, 2024).
aortic aneurysm (continued). "The SLC44A2/NRP1/ITGB3 complex is a major regulator of vascular smooth muscle cell phenotypic switching and a target of lenalidomide in aortic aneurysm treatment." (PMID 38916960, 2024). "Here, we report SLC44A2 as a key regulator of VSMC phenotypic switching, participating in the progression of aortic aneurysm." (PMID 38916960, 2024). "SLC44A2 interacts with neuropilin-1 (NRP1) to activate transforming growth factor β (TGF-β) signaling in an integrin β3–dependent (ITGB3-dependent) manner, which maintains VSMCs’ contractile phenotype and alleviates aortic aneurysm." (PMID 38916960, 2024). "Lastly, LEN may upregulate RUNX1 to increase SLC44A2 expression, ameliorating VSMC phenotypic switching and protecting against aortic aneurysm." (PMID 38916960, 2024). "Additionally, lenalidomide (LEN) administration enhances SLC44A2 expression primarily through runt-related transcription factor 1 (RUNX1), leading to improvements in aortic aneurysm conditions, which provides a potential new therapeutic strategy for aortic aneurysm." (PMID 38916960, 2024).
COVID-19 (2 papers, 2023 to 2025). A disease caused by infection with severe acute respiratory syndrome coronavirus 2. "GWAS have suggested a role for SLC44A2 in regulating thrombosis, which involves mitochondria in platelets; this is of particular interest as formation of microthrombosis in cerebral vessels is considered a major cause of brain pathology in COVID-19." (PMID 40667466, 2025). "Up to this point there is no data available on SLC44A2 in COVID-19 and how it could potentially impact CAC except for fundamental proteomic data which suggests a significant downregulation of SLC44A2 in neutrophils from severe COVID-19 patients." (PMID 37275917, 2023).
osteoarthritis (2 papers, 2021 to 2024). A noninflammatory degenerative joint disease occurring chiefly in older persons, characterized by degeneration of the articular cartilage, hypertrophy of bone at the margins and changes in the synovial membrane. "We found strong evidence for co-localisation of five osteoarthritis signals with cartilage molQTLs for ALDH1A2, NPC1, SMAD3, FAM53A and SLC44A2." (PMID 33637762, 2021). "Several osteoarthritis GWAS signals were found to co-localise with eQTLs in only 1 or 2 of 53 tissues (e.g. ALDH1A2: ovary and tibial artery, SMAD3: skeletal muscle; SLC44A2: adrenal gland), without clear transferability of results to disease-relevant tissue." (PMID 33637762, 2021).
pancreatic adenocarcinoma (2 papers, 2020 to 2025). "Conversely, lower SLC44A2 expression was associated with better survival in pancreatic adenocarcinoma (PAAD), invasive breast cancer (BRCA), and adrenocortical carcinoma (ACC)." (PMID 40592838, 2025). "In contrast, patients with lower SLC44A2 expression in pancreatic adenocarcinoma (PAAD), invasive breast carcinoma (BRCA), and adrenocortical carcinoma (ACC) had better OS than those with higher SLC44A2 expression." (PMID 40592838, 2025).
thrombosis (2 papers, 2020 to 2022). "The INVENT Consortium used GWAS to identify genetic variants associated with VTE in a cohort of over 60,000 human subjects, including a genetic variant located within the gene SLC44A2 which was associated with a ~20% increased risk of thrombosis in replication and discovery cohorts." (PMID 32661250, 2020).
abdominal aortic aneurysm (1 paper, 2024). Enlargement and ballooning of the vessel that supplies arterial blood to the abdomen, pelvis and legs. "Elevated levels of SLC44A2 were evident in the aorta of both patients with abdominal aortic aneurysm and angiotensin II–infused (Ang II–infused) Apoe–/– mice." (PMID 38916960, 2024). "Importantly, we further verified that SLC44A2 protein and mRNA levels were significantly increased in patients with abdominal aortic aneurysm (AAA), with immunostaining indicating higher SLC44A2 levels in the media layer of human AAA aortas compared with controls." (PMID 38916960, 2024).
colorectal cancer (1 paper, 2025). A primary or metastatic malignant neoplasm that affects the colon or rectum. "In the present investigation, we observed a significant reduction in SLC44A2 expression in colorectal cancer (CRC), and low SLC44A2 expression was closely associated with poorer survival of CRC patients." (PMID 40592838, 2025). "In this study, we observed a marked reduction in SLC44A2 expression in colorectal cancer (CRC) and found that low SLC44A2 expression was significantly correlated with increased tumor size, higher incidence of tumor thrombus, and poorer survival in CRC patients." (PMID 40592838, 2025). "We first examined the expression of SLC44A2 in colorectal cancer (CRC) using the UALCAN database." (PMID 40592838, 2025).
epilepsy (1 paper, 2023). A brain disorder characterized by episodes of abnormally increased neuronal discharge resulting in transient episodes of sensory or motor neurological dysfunction, or psychic dysfunction. "Interestingly, in the proband 2 family, the homozygous SLC44A2 null allele was associated with more severe diseases, including ICA and epilepsy." (PMID 36695047, 2023). "Interestingly, we demonstrate that a large homozygous deletion in SLC44A2 gene results in the total absence of this protein in three siblings, all of whom suffer from age‐related hearing loss, and some of them from epilepsy or intracranial aneurysms." (PMID 36695047, 2023).
glioma (1 paper, 2025). A benign or malignant brain and spinal cord tumor that arises from glial cells (astrocytes, oligodendrocytes, ependymal cells). "Pan-cancer analysis revealed that lower SLC44A2 expression was also associated with poorer survival in several other cancers, including clear cell carcinoma of the kidney (KIRC), glioma (GBMLGG), head and neck squamous cell carcinoma (HNSC), and skin cutaneous melanoma (SKCM)." (PMID 40592838, 2025). "Kaplan-Meier survival analysis showed that patients with lower SLC44A2 expression had worse overall survival (OS) in renal clear cell carcinoma (KIRC), pan-kidney cohort (KIPAN), glioma (GBMLGG), head and neck squamous cell carcinoma (HNSC), and skin cutaneous melanoma (SKCM)." (PMID 40592838, 2025).
head and neck squamous cell carcinoma (1 paper, 2025). A squamous cell carcinoma that arises from any of the following anatomic sites: lip and oral cavity, nasal cavity, paranasal sinuses, pharynx, larynx, and salivary glands. "Among the 26 TCGA cancer types, SLC44A2 was significantly downregulated in lung adenocarcinoma (LUAD), lung squamous cell carcinoma (LUSC), renal papillary cell carcinoma (KIRP), renal clear cell carcinoma (KIRC), prostate adenocarcinoma (PRAD), and head and neck squamous cell carcinoma (HNSC)." (PMID 40592838, 2025).
metastasis (1 paper, 2025). The spread or migration of cancer cells from one part of the body (where they first appeared) to another. "Correlation analysis revealed that SLC44A2 downregulation was significantly associated with larger tumor size and higher frequency of lymph node metastasis." (PMID 40592838, 2025).
sarcopenia (1 paper, 2025). Progressive decline in muscle mass due to aging which results in decreased functional capacity of muscles. "In this context, mitochondrial dysfunction–related genes such as SLC44A2, TPM3, PIPOX, and DHDPSL, which are represented among the 20 CpGs identified in our study, may play a contributory role in the pathophysiology of sarcopenia." (PMID 41297061, 2025).
thrombotic disorders (1 paper, 2020). "As platelet-leukocyte interactions are involved in both of these thrombotic disorders, we hypothesized that SLC44A2 functions as the neutrophil counter receptor for activated αIIbβ3." (PMID 32314961, 2020).